LAG3 (lymphocyte activating 3)
Diseases named in the same sentence as LAG3 in open-access papers (continued):
Sharing a sentence is not in itself a finding about the gene and the disease.
multiple myeloma (continued). "Furthermore, in the Tim3+PD-1+ CD8 T cells, two inhibitory molecules, TIGIT- and LAG3- double-positive cells were increased by myeloma transplantation and the increment was cancelled by cDC1 depletion." (PMID 39474418, 2024). "In stem cell-based therapy LAG3 rs870849 may promote T cell activity against myeloma cells." (PMID 41614836, 2025). "This study might provide new clinical evidence for the role of PD-1 and LAG-3 in multiple myeloma." (PMID 36529769, 2022). "In summary, this prospective observational study demonstrated that the frequency of PD-1+ and LAG-3+ T cells were correlated with clinical outcomes and prognosis of relapsed/refractory multiple myeloma patients, which might also be used as potential biomarkers for the relapsed/refractory stage." (PMID 36529769, 2022). "In addition, it is known that CD8+ T cells from myeloma patients co-express other immune checkpoints, such as LAG-3, TIM-3, CTLA4, and TIGIT suggesting multiple pathways limiting T-cell responses at this stage of disease and thus explaining the lack of effect from PD-L1/PD-1 blockade as monotherapy." (PMID 33488620, 2020). "Deletion of TIM-3, LAG-3, and 2B4 genes by CRISPR-Cas9 led to superior functionality and resistance to exhaustion of transgenic TCR NY-ESO-1-specific T cells in preclinical myeloma models." (PMID 41181132, 2025). "LAG3 can be used as a target for cancer immunotherapy, targeting LAG3/GAL-3 to overcome immunosuppression and enhances the antitumor immune response in multiple myeloma." (PMID 37143720, 2023). "Our finding of LAG-3 expression on malignant PCs strongly supports its possible role in predicting the progression of MGUS and SMM into symptomatic multiple myeloma." (PMID 38203720, 2023). "Studies in the 5T33 murine myeloma model already showed the efficacy of lenalidomide in combination with blockade of other immune checkpoints (e.g. CTLA-4, LAG-3, TIM-3, and combinations thereof)." (PMID 27809856, 2016). "We observed increased expression of TIM-3, LAG-3, CTLA4, and 2B4 on both CD8 and CD4 T cells in myeloma-bearing mice, and anti-myeloma synergy occurred when the PD-1/PD-L1 axis was blocked in combination with blocking TIM-3, LAG-3, or CTLA4." (PMID 25614821, 2015). "The reason could be that sustained Type I IFN signaling is key for the expansion of LAG3+ Tregs, as it was shown that blocking type I IFNs receptor by IFNAR1 antibody hindered myeloma-driven LAG3+ Treg expansion." (PMID 37833265, 2023). "In fact, the expression of the checkpoint inhibitory molecules PD-1, TIM3, LAG3, and TIGIT has long been associated with lack of T-cell fitness and increased incidence of multiple myeloma relapse." (PMID 36874402, 2022). "The elucidation of additional costimulatory drugs potentiating LAG-3 blockade, and the effect of combining LAG-3 blockade with immunomodulatory drugs in other hematological malignancies typically displaying LAG-3 dysregulation, such as multiple myeloma, warrants further investigations." (PMID 33925565, 2021). "Among the stable myeloma precursor condition cases, we identified only 11 SV hotspots: all translocations between the IGH locus and CCND1 (n = 7), MAFB (n = 2), CCND3 (n = 1), and LTBR|LAG3 (n = 1)." (PMID 33767199, 2021). "In summary, prior to advanced 5T33 myeloma burden, there are splenic PD-1+ T cells that appeared to be chronically activated, as demonstrated by expression of activation markers CD69, OX-40 and CD103, and inhibitory receptors LAG-3 and TIM-3." (PMID 28642819, 2017). "Although our results showed an upregulation of genes associated to cytotoxicity in the BM of patients with SMM compared to MGUS, we also found overexpression of inhibitory molecules such as LAG-3, TIGIT and IDO1, which may affect the anti-myeloma immune response in SMM." (PMID 34880879, 2021). "However, we also found overexpression of inhibitory molecules such as LAG-3, TIGIT and IDO1, which may affect the anti-myeloma immune response in SMM." (PMID 34880879, 2021).
multiple myeloma (continued). "Interestingly, the analysis of secreted pro-inflammatory cytokines and effector molecules showed that TIM-3-, LAG-3-, and 2B4-disrupted TCRED T cells produce higher amounts of IL-2, TNFα, sFasL and perforin compared to TCRED-IRCOMP T cells when tested with the two different multiple myeloma models." (PMID 38510235, 2024). "PD-1, TIGIT, TIM3, and LAG3 expression by MFI was not significantly different between HD and late relapsed multiple myeloma CAR T-cell products." (PMID 36874402, 2022). "PD-L1 is highly expressed on 5T33 myeloma cells, but the ligands for TIM-3 (galectin-9), LAG-3 (MHC class II), and CTLA4 (CD80) are not." (PMID 25614821, 2015).
malaria (28 papers, 2014 to 2026). Malaria is a serious and sometimes fatal disease caused by a parasite that commonly infects a certain type of mosquito which feeds on humans. "Previous work in a mouse model of malaria caused by Plasmodium falciparumyoelii 17XNL found combined neutralization of PD-1 and LAG3 signaling was required to enhance antiparasitic immunity." (PMID 37917177, 2023). "However, blockade of CTLA-4, LAG3 and PD-L1 was insufficient to restore control of S. Typhimurium infection, suggesting that additional effects of malaria on immunity to S. Typhimurium may be responsible for loss of vaccine-mediated protection." (PMID 26366739, 2015). "Butler and colleagues reported that the combination treatment with anti–PD-L1 and anti-LAG3 mAb during established malaria enhances TFh responses, plasma cell formation, and protective antibody generation in a mouse model of malaria." (PMID 40359031, 2025). "Administration of anti‐PD‐L1 and anti‐LAG‐3 monoclonal antibodies accelerated parasite clearance and increased the number and function of malaria‐specific T cells." (PMID 39248154, 2024). "On the contrary, in a murine model of malaria, T-cells expressing co-inhibitory receptors, such as PD-1 and LAG-3, were shown to be more functional.Therefore, these observations should be followed up with further functional analyses." (PMID 35746736, 2022). "We have recently shown that blood-stage malaria in experimental models but also in human malaria is accompanied by an induction of co-inhibitory molecules like PD-1, LAG-3, and TIM-3 on CD4+ as well as CD8+ T cells." (PMID 35874786, 2022). "Previous studies of T cells in malaria have shown that the upregulation of co-inhibitory molecules such as LAG-3 and TIM-3 in response to acute infection can have both beneficial and detrimental effects." (PMID 32983106, 2020). "In summary, LAG-3 blockade contributes to rescuing malaria-induced CD4+ T cell dysfunction in PD-L1-/- mice, but does not appear to modulate their ability to differentiate into various functional and memory subsets of T cells." (PMID 33519801, 2020). "Even though we could only measure a limited impact of LAG-3/PD-L1 blockade on the immune response, the treatment significantly diminishes blood parasitemia (~30% from day ~12 and on), which may be essential in limiting the excessive inflammation associated with severe malaria." (PMID 33519801, 2020). "LAG-3 was downregulated in cluster group I, indicating a lower expression in children with uncomplicated malaria." (PMID 29555909, 2018). "In a murine malaria model, blocking PD-1 pathway in combination with blocking LAG3 signaling reduced parasitemia, improved T cell responses and improved antibody responses resulting in parasite clearance and extended survival of the mice." (PMID 29987244, 2018). "It is interesting to note in this context that both IL-10 blockade and blockade of PDL-1, CTLA4 and LAG3 reduced the level of circulating malaria parasites, however only IL-10 blockade restored vaccine-mediated protection." (PMID 26366739, 2015). "The combined blockade of PD-L1 and LAG-3 inhibitory molecules with antibodies, during P. yoelii and P. chabaudi malaria in mice accelerated clearance of parasitemia." (PMID 24904561, 2014). "Similarly, LAG-3 was increased on both Vδ2+ and Vδ1+ γδ T cells during malaria but TIM-3 was only increased in Vδ2+ γδ T cells." (PMID 37968278, 2023). "Thus, malaria-induced CD8+ T cells co-express LAG-3, PD-1, TIGIT, TIM-3, CTLA-4, and CD39 but similarly express more effector molecules compared to those expressing lower levels of co-inhibitory molecules." (PMID 35874786, 2022). "We found that PD-1+, 4-1BB+, LAG-3+, KLRG1–, PLZF–, CTLA4+, and Siglec-7– NK cells were increased in individuals with malaria experience." (PMID 40337867, 2025). "In murine malaria models, PD-1, TIM-3, and LAG-3 blockade leads to an enhancement of pro-inflammatory T-cell responses and a more severe course of disease." (PMID 38265549, 2024).
malaria (continued). "PD-1 and LAG-3 are highly expressed in CD4+ and CD8+ T cells, and the expansion of such cells among peripheral blood mononuclear cells in malaria-infected patients has been reported." (PMID 38265549, 2024). "A subset of adaptive NK cells characterized by the lack of CD56 (NCAM1) and higher expression of inhibitory receptors LAG3 (CD223) and LILRB1 (CD85j) correlated with reduced parasitemia and protection against malaria symptoms in the subsequent year." (PMID 37939134, 2023). "Blockade of CTLA-4 and other inhibitory receptors, e.g., lymphocyte-activation gene-3 (LAG-3), programmed death-1 (PD-1), and T-cell immunoglobulin mucin-3 (TIM-3), improved T-cell responses to malaria parasites." (PMID 34395313, 2021). "Overexpression of inhibitory molecules such as PD-1, LAG-3, or BTNL-2 on antigen-experienced T cells in malaria-infected patients were suggested as possible mechanisms accounting for the impaired development of effective and long-lasting adaptive immunity." (PMID 33519801, 2020). "Accordingly, we observed a significant increase of LAG-3 and TIM-3 on CD8+ and CD4+ T cells in malaria patients when compared to healthy donors." (PMID 32983106, 2020). "Expression of high levels of PD-1 and LAG-3 on CD4+ and CD8+ T cells, and expansion of such cells among peripheral blood mononuclear cells (PBMCs) of malaria-infected patients has been reported." (PMID 33519801, 2020). "T cells expressing multiple checkpoint markers, including PD‐1 and LAG‐3,137, 147, 148, 149, 150 CTLA‐4,149, 150, 151 OX40,151 and Tim‐3137, 149, 150, 152, 153 have been shown to be upregulated during infection with malaria in humans and contribute to immunosuppression." (PMID 39248154, 2024). "Evidence of malaria induced immunosuppression within our data was also observed in NK and γδ T cell subsets, where multiple co-inhibitory receptors were upregulated during infection (including TNFRSF4, TNFRSF9, TNFRSH18, HAVCR2, LAG3, and PDCD1)." (PMID 37968278, 2023). "For example, CD8+ T-cell exhaustion can be characterized by a number of cell surface markers including PD-1, Tim-3, LAG-3, and IL-10 plasma levels, and earlier studies already identified that PD-1 dependent exhaustion of CD8+ T cells in malaria facilitated a chronic disease state." (PMID 34485170, 2021). "In this work, we investigated the mechanisms by which blockade of the inhibitory receptors LAG-3 and PD-L1 promote more effective control and clearance of non-lethal blood stage murine P. yoelii malaria." (PMID 33519801, 2020). "Both PD-1 and LAG-3 inhibitory molecules are also upregulated in various surrogate non-lethal mouse models of blood stage malaria, and, as in chronic viral infections and tumors, their selective blockade accelerates pathogen elimination." (PMID 33519801, 2020). "However, in malaria patients we found high levels of single-positive PD1+LAG-3− and PD1+TIM-3− as well as high levels of double-positive PD1+LAG-3+ and PD1+TIM-3+ CD8+ and CD4+ T cells." (PMID 32983106, 2020). "In malaria, work in both human and murine models has reported the upregulation of immune inhibitory markers such as T-cell immunoglobin and mucin domain-3 (TIM-3), lymphocyte-activation gene-3 (LAG-3) and programmed cell death-1 (PD-1) during acute infections." (PMID 31316497, 2019). "In cluster group II, LAG-3 showed a higher than background expression only in cluster 6, signifying a higher expression of LAG-3 for one T cell cluster in children with complicated malaria." (PMID 29555909, 2018). "Increased proportions of CD4+ T cells express CTLA-4, OX40, Glucocorticoid-induced TNFR family related gene (GITR), tumor necrosis factor alpha receptor type II (TNFRII), PD-1, LAG3, T-cell immunoglobulin and mucin-3 (TIM3) and CD69 during P. vivax and P. falciparum malarias." (PMID 30631323, 2018). "In addition to elevated PD-1 and LAG3 expression on CD8+ T cells, higher frequencies of CD4+ T cells expressing PD-1 are observed in malaria-infected children in Mali." (PMID 29987244, 2018).
malaria (continued). "However, PD1+ NK cells are the most highly activated and regulatory during malaria due to the increased overall level of expression of these markers during acute infection, particularly CD98, HLA-DR, LAG-3 and TIM-3, compared to adaptive and CD56bright NK cells." (PMID 37968278, 2023). "Additionally, DCs of humans inflicted with malaria mediated strong immunosuppression through the induction of Indoleamine 2,3-Dioxygenase 1(IDO1) and Lymphocyte Activation Gene 3 (LAG3), which attenuates inflammatory response by decreasing class II antigen presentation." (PMID 34414129, 2021). "Likewise, a combined blockade of the inhibitory molecules PDL1 and lymphocyte activation gene 3 protein (LAG3), accelerate the clearance of acute non-lethal Plasmodium yoelii malaria." (PMID 32599864, 2020). "Here, results of our univariate approaches could be confirmed by the multivariate analysis which identified a cluster group of T cells which was more frequent in children with complicated malaria than uncomplicated malaria and showed increased expression of CTLA-4, PD-1 and partially LAG-3." (PMID 29555909, 2018). "Furthermore, combined blockade of PD-L1 and Lymphocyte-activation gene 3 (LAG3) immune inhibitory molecules accelerated clearance of non-lethal P. yoelii blood-stage malaria by improving CD4+ T cell functions and increasing antibody titres." (PMID 30631323, 2018). "Thus, we propose a model in which inhibition of LAG-3 on parasite-specific CD4+ T cells unleashes their ability to produce effector cytokines, altogether contributing to achieve superior levels of protection in malaria-infected hosts, independent from parasite-specific humoral responses." (PMID 33519801, 2020). "The PD1+CTLA4+ T cells in our malaria patients were clearly distinct from natural Tregs as they did not express Foxp3 or CD25, nor were they CD49b+LAG3+, which are recently identified markers for Tr1 cells." (PMID 27802341, 2016). "The here identified T cell cluster which was more abundant in children with complicated malaria showed an increased expression of CTLA-4, PD-1 and partially LAG-3, but did not belong to the group with the highest expression levels of these co-inhibitory molecules." (PMID 29555909, 2018).
leukemia (27 papers, 2015 to 2026). A malignant (clonal) hematologic disorder, involving hematopoietic stem cells and characterized by the presence of primitive or atypical myeloid or lymphoid cells in the bone marrow and the blood. "T-cell populations from vehicle treated mice with leukemia exhibited significant upregulation of genes associated with immune exhaustion, such as Lag3, Tigit and Il10, as well as Ms4a2, an immune suppressive gene expressed by T-regulatory cells." (PMID 35831470, 2022). "RNA-sequencing of T-cells isolated from vehicle and rIL-12 treated mice with B-ALL revealed that the leukemia-induced increase in genes associated with exhaustion, including Lag3, Tigit, and Il10, was abrogated with rIL-12 treatment." (PMID 35831470, 2022). "On the other hand, lymphocyte activation gene-3 (LAG-3) deficient anti-CD19 CAR T cells potently induced robust antigen-specific anti-leukemia impacts in vitro and in NPG mice." (PMID 35093187, 2022). "Increasing the expression of LAG-3 and LAG-3+ immune cells in patients with solid tumors or leukemia has been associated with tumor progression, poor prognosis, and unfavorable clinical outcomes, strongly indicating that LAG-3 contributes to immune escape by tumor cells." (PMID 37670328, 2023). "Collectively, this macrophage repolarization had downstream effects on T cells within the leukemia microenvironment, including decreased PD-1+Tim-3+ and LAG3+ checkpoint expression, and increased CD69+CD107a+ expression." (PMID 36960055, 2023). "Restored expression of Tbet and a Tbet dependent increase in IFN-γ and CXCR3 expression was also found after combined check-point blockade (PD-1, CTLA-4, and LAG-3) in a murine leukemia model." (PMID 33193386, 2020). "In mice with advanced leukemia, antigen-specific CTLs were also expanded, but were unresponsive to antigen stimulation and expressed high levels of PD-1 and LAG-3." (PMID 26658107, 2015). "T cells from mice that failed to achieve leukemia clearance exhibited expression of exhaustion-associated genes, including LAG3 and TIGIT." (PMID 40503229, 2025). "The expression patterns of Tregs-associated markers (CD25, LAG-3, killer cell lectin like receptor G1, CD69, Eomesodermin - EOMES) that determines their suppressive functions was recently presented in both CLL patients and leukemia-bearing mice." (PMID 35296093, 2022). "Our finding that the expression of TIGIT and LAG3 is increased in marrow-infiltrating T cells supports specific evaluation of these targets, already under active investigation in adult cancers, in pediatric leukemia." (PMID 32692727, 2020). "LAG-3 expression was also significantly higher in CTLs from the mice with advanced leukemia." (PMID 26658107, 2015). "An extensive head-to-head comparison of CAR T cells with double knockdown of PD-1 and either LAG3, TIM3, or TIGIT in mice bearing NALM6 leukemia showed superior therapeutic efficacy of CAR T cells with simultaneous knockdown of PD-1 and TIGIT." (PMID 40558528, 2025). "In a syngeneic murine model of TCF3::PBX1 leukemia, an upregulation of PD-1, TIM-3, and LAG3 on CD4+ and CD8+ T cells was observed in the presence of leukemia." (PMID 40503229, 2025). "In this review, we describe the gene and protein characteristics, biological functions, and abnormal expression profiles of LAG-3, TIM-3, and TIGIT in solid tumors and leukemia." (PMID 37670328, 2023). "The elevated expression of LAG-3 was achieved only when Tregs-GFP+ and TCL1 leukemia cells were cultured in direct contact." (PMID 35296093, 2022). "Our results indicate that the phenotype of Tregs changes during the course of leukemia to establish a subpopulation of CD4+, FoxP3+, LAG-3+, CD69hi, and surprisingly, CD44lo and CD25lo cells." (PMID 35296093, 2022). "Deeper analyses using single-cell RNA sequencing of one patient sample revealed that LAG3 and TIM3 were overexpressed in leukemia antigen-specific T cells." (PMID 33746972, 2021).